PTPRD (protein tyrosine phosphatase receptor type D)
Diseases named in the same sentence as PTPRD in open-access papers (continued):
Sharing a sentence is not in itself a finding about the gene and the disease.
metastatic colorectal cancer (2 papers, 2021 to 2023). "Deleterious mutations or copy number loss of PTPRT and its related gene PTPRD are potential markers for evaluating resistance to bevacizumab regimens and are closely associated with shorter PFS in metastatic colorectal cancer patients." (PMID 37158817, 2023).
osteosarcoma (2 papers, 2014 to 2022). A usually aggressive malignant bone-forming mesenchymal neoplasm, predominantly affecting adolescents and young adults. "Given that PTPRD inactivation may increase STAT3 activity, the use of STAT3 inhibitors may have relevance in the treatment of osteosarcomas with PTPRD mutations." (PMID 25126591, 2014).
rectal tumors (2 papers, 2018 to 2019). "In multivariate analysis, both postulated deleterious PTPRT/PTPRD alterations and rectal tumors were independent factors associated with shorter PFS (HR, 3.33; 95% CI, 1.47–7.54; p = 0.0038 and HR, 2.56; 95% CI, 1.23–5.32; p = 0.0118, respectively)." (PMID 30200630, 2018). "We have previously shown that when considering clinical factors and PTPRT and PTPRD deleterious alterations, rectal tumors and PTPRT and PTPRD deleterious alterations were independent predictors of short PFS." (PMID 31366114, 2019).
resistant hypertension (2 papers, 2021). "SNP rs10809095 was located on the protein tyrosine phosphatase receptor type D gene (PTPRD, OMIM accession number: 601598), which was associated with resistant hypertension in multiple ethnic groups, but the mechanism is still unclear." (PMID 34586716, 2021).
uterine corpus endometrial carcinoma (2 papers, 2022 to 2024). A endometrial carcinoma (disease) that involves the body of uterus. "A subsequent analysis of PTPRD expression in both healthy and cancerous brains (GBM) and endometrial (uterine corpus endometrial carcinoma, UCEC) samples revealed a significant downregulation of the gene in the tumour cohort, with a statistical significance of p < 0.01." (PMID 38339334, 2024).
autoimmune thyroid disease (1 paper, 2023). Inflammatory disease of the thyroid gland due to autoimmune responses leading to lymphocytic infiltration of the gland. "In TCGA-LUSC cohort, autoimmune thyroid disease, glycosphingolipid biosynthesis ganglio series, other glycan degradation, bile acid biosynthesis, and regulation of autophagy were significantly abundant in PTPRD mutation samples." (PMID 37602864, 2023).
B-cell lymphomas (1 paper, 2021). "Further, mutations in PTPRD have recently been shown to be frequent in T-cell rich B-cell lymphomas that display MLH1 haploinsufficiency, adding weight to the validity of our co-expression analysis." (PMID 33889300, 2021).
breast tumours (1 paper, 2018).
carpal tunnel syndrome (1 paper, 2022). Entrapment of the median nerve in the wrist that is characterized by numbness, tingling and painful movement. "Here, we investigated the role of PTPRD in the CCI-induced neuropathic pain, as CCI exhibits a similar pathophysiologic mechanism with carpal tunnel syndrome, which is the most common peripheral nerve chronic compression disease." (PMID 35493326, 2022).
cervical cancer (1 paper, 2015). A primary or metastatic malignant neoplasm involving the cervix. "PTPRD copy number alterations occur to a substantial degree in HNSCC and other cancers, where gene copy loss, particularly heterozygous loss, occurs more frequently than gain in HNSCC and all cancers analyzed with the exception of colorectal and cervical cancers." (PMID 26267899, 2015).
COVID-19 (1 paper, 2022). A disease caused by infection with severe acute respiratory syndrome coronavirus 2. "After comparing the significant genes in T2D and COVID-19, five genes were found to be shared between T2D and COVID-19: PTPRD, CSMD1, MAGI1, ASIC2, DAB1." (PMID 36482905, 2022). "Further, in our gene-based analysis, five genes (DAB1, ASIC2, MAGI1, CSMD1 and PTPRD) were shared between T2D and COVID-19." (PMID 36482905, 2022). "Among the shared genes between T2D and COVID-19 by PASCAL, the PTPRD gene encodes a member of the protein tyrosine phosphatase family which regulates cellular processes including differentiation and cell growth." (PMID 36482905, 2022).
Dandy-Walker malformation (1 paper, 2016). "Furthermore, our data suggests the involvement of CNTN6 and KLHL15 in the etiology of agenesis of the corpus callosum, the involvement of RASD1 and PTPRD in Dandy-Walker malformation, and the involvement of ERMARD in ventriculomegaly." (PMID 27087860, 2016).
dentin caries (1 paper, 2026). "For instance, pharmacological inhibition of MARCH2 activity or stabilization of PTPRD could potentially enhance odontoblast differentiation, offering therapeutic benefit in conditions such as dental pulp injury or dentin caries." (PMID 41513627, 2026).
depressive disorder (1 paper, 2024). A melancholy feeling of sadness and despair. "Interestingly, three other tyrosine phosphatase protein receptor genes (PRPRR, PTPRD, and PTPRS), were found to be significantly associated with depressive disorder." (PMID 38555957, 2024).
endometrial adenocarcinoma (1 paper, 2024). "Interestingly, in BeWo cells (cytotrophoblasts), as well as in NOU-1 (a poorly differentiated endometrial adenocarcinoma cell line), PTPRD was also localised in the nucleus." (PMID 38339334, 2024).
gastric tumor (1 paper, 2014). "Quantitative real time reverse transcription PCR (qRT-PCR) and western blotting were used to examine PTPRD expression in paired gastric tumourous and paracancerous tissues." (PMID 25412184, 2014). "The statistical evaluation showed significantly decreased expression of PTPRD in gastric tumor tissues compared with matched adjacent noncancerous tissues (P = 0.0093)." (PMID 25412184, 2014).
injury (1 paper, 2025). Damage inflicted on the body as the direct or indirect result of an external force, with or without disruption of structural continuity. "In vivo validation demonstrated that NSUN2 promoted A1 astrocyte activation through PTPRD, exacerbating traumatic brain injury-induced brain damage." (PMID 41462962, 2025). "NSUN2 enhances the m5C methylation stability of PTPRD mRNA, exacerbating A1 astrocyte activation and the subsequent inflammation-mediated tissue damage after traumatic brain injury." (PMID 41462962, 2025).
keloid (1 paper, 2024). An irregularly shaped, elevated mark on the skin caused by deposits of excessive amounts of collagen during wound healing. "Of those, six genes (i.e., OPCML, S100A7, S100 calcium binding protein A8 [S100A8], KANK4, PTPRD, tenascin XB [TNXB]) were significantly differentially expressed between keloid and immature scar samples." (PMID 38622256, 2024).
lymph-node metastasis (1 paper, 2020). "Other factors like FAT3, APC, PTPRD (P = 0.01), lymph-node metastasis, EPHA3, TERT, and STK11 (P = 0.05) that have been found to be related to TMB distribution." (PMID 33996530, 2020).
malignant glioma (1 paper, 2014). A grade III or grade IV glioma arising from the central nervous system. "Their results suggest that PTPRD may act as a tumor suppressor by regulating cell growth, and the loss of this gene plays an important role in progression, rather than the initiation of malignant gliomas." (PMID 25412184, 2014).
MALT lymphoma (1 paper, 2021). An indolent, extranodal type of non-Hodgkin lymphoma composed of small B-lymphocytes (centrocyte-like cells). "Conversely, NMZLs display an inactivation of PTPRD (14% in NMZLs vs. 3% in MALT lymphomas) and a much higher prevalence of mutations affecting KMT2D (34% in NMZL vs. 15% in MALT lymphomas)." (PMID 34590593, 2021).
medulloblastoma (1 paper, 2012). A malignant, invasive embryonal neoplasm arising from the cerebellum. "Thus, PTPRD is likely to have a tumor suppressor function in any type of cancer with MYCN amplification, including other pediatric cancers such as medulloblastoma and rhabdomyosarcoma, or in adult tumors that are dependent on high AURKA levels." (PMID 22305495, 2012).
metastatic disease (1 paper, 2018). "It is necessary to underline that although mutated ERBB2, PTPRT, PTPRD and AURKB predicted poor OS in univariate analysis they were excluded from the multivariate analysis because they were preferentially identified in patients with late stage (stage III-IV) and/or metastatic disease." (PMID 29844865, 2018).
myeloid malignancies (1 paper, 2017). "Most of the significantly mutated genes were previously well documented either in MDS or other myeloid malignancies, although some were newly identified or re-confirmed as recurrently mutated genes in our analysis, such as ROBO1/2, IHIT3, KIF20B, PTPRD, ANKRD11 and DHX9." (PMID 28220884, 2017).
neural tumors (1 paper, 2025). "Overall, by comparing to PA, we identified subtype-specific pathways in neural tumors: PAK signaling (PTPRD and PDGFRB) in GBM, regulation of CFTR activity pathway (PPP2R1A, RABEP1) in MBL, and ERK signaling (IRS4 and ATM) in NBL." (PMID 40768543, 2025).
neurofibroma (1 paper, 2023). An intraneural or extraneural neoplasm arising from nerve tissues and neural sheaths. "We observed PTPRD mutations in 2 of 19 atypical neurofibromas (11%) and 2 of 7 MPNST-G2 tumors (29%)." (PMID 37164978, 2023). "Notably, we report a mechanism of PTPRD inactivation through mutations, which were private to atypical neurofibromas and MPNST-G2 tumors." (PMID 37164978, 2023). "Additional recurrent but low-frequency mutations in neurofibromas include FANCA, PTPRD, NF2, LZTR1, KNL1 and RUNX1." (PMID 37164978, 2023).
nodal marginal zone lymphoma (1 paper, 2024). "Somatic variants in PTPRD and BRAF genes are highly prevalent in nodal marginal zone lymphoma (NMZL)." (PMID 38835967, 2024).
osteoporosis (1 paper, 2025). A condition of reduced bone mass, with decreased cortical thickness and a decrease in the number and size of the trabeculae of cancellous bone (but normal chemical composition), resulting in increased fracture incidence. "Bae J-H, Park D. Effect of dietary calcium on the gender-specific association between polymorphisms in the PTPRD locus and osteoporosis." (PMID 40411668, 2025). "Bae and Park (2022) demonstrated that dietary calcium intake modulated the effects of variants in the PTPRD locus, with an increased risk of osteoporosis observed in Korean women with low calcium intake [69•]." (PMID 40411668, 2025).
salivary gland tumors (1 paper, 2022). "Of note, our NGS panel has routinely identified HMGA2 translocations with diverse downstream partners e.g., HMGA2::PTPRD, HMGA2::WIF1, and HMGA2::ACTR6 in three recent salivary gland tumors (carcinoma ex pleomorphic adenoma) that characteristically harbor HMGA2 rearrangements." (PMID 35798968, 2022).
tauopathies (1 paper, 2025). "This indicates a new potential therapeutic approach for tauopathies, where PTPRD could serve a protective role against tau-related pathologies and may act as a key modulator in disease progression." (PMID 40329347, 2025).
tumor (103 papers, 2008 to 2025). "The PTPRD gene encodes a transmembrane receptor protein, tyrosine phosphatase, with tumour suppressor functions." (PMID 38778183, 2024). "Sequencing of a post‐treatment tumor sample from patient 14 showed a de‐novo PTPRD c.3715‐1G > T splice region variant." (PMID 37644890, 2023). "DDR and MMR gene mutations, which can increase tumor immunogenicity and promote anti-tumor immunity, were more frequent in the PTPRD/PTPRT mutant cancer patients than in the WT patients." (PMID 36248841, 2022). "PTPRD DNA copy number losses, which were mainly hemizygous losses, were recurrently detected in all the tumor types within 581 diffuse glioma cases and associated with reduced PTPRD expression." (PMID 35982066, 2022). "Consistently, PTPRD/PTPRT mutations are associated with tumor progression and a worse patient prognosis." (PMID 36248841, 2022). "PTPRD has been implicated as a tumor suppressor in several cancers with inactivating somatic variants found in >50% of GBM and between 10% and 20% of head and neck mucosal SCC (HNSCC)." (PMID 35982973, 2022). "PTPRD phosphatase domain mutations in tumor tissue predicted OS and that in ctDNA served as a predictive biomarker helping select patients benefiting from ICIs in non-squamous NSCLC (ns-NSCLC)." (PMID 34615542, 2021). "In the further exploratory analysis, PTPRD/PTPRT mutation was significantly associated with increased tumor mutation burden and higher mRNA expression of JAK1 and STAT1." (PMID 34123798, 2021). "Regarding tumor sites, it has further been reported that splenic flexure tumors have a high proportion of PTPRD mutations." (PMID 30200630, 2018). "Loss of CDKN2A/CDKN2B or PTPRD tumor suppressor was often used to explain the frequent chromosome 9p deletion in human cancer." (PMID 28977839, 2017). "Mutation or epigenetic silencing of PTPRD has been reported for the loss of tumor suppressor role in several cancers." (PMID 27501229, 2016). "The PTPRD S1845fs*2 mutation detected in Patient #1′s tumor is an altered tumor suppressor gene that dephosphorylates the oncoprotein Stat3, thus inactivating it." (PMID 26510912, 2015). "Data showed that tumor infiltration, local lymph node metastasis, distant metastasis, TNM stage, tumor size and PTPRD expression were significantly associated with overall survival." (PMID 25412184, 2014). "The protein encoded by the PTPRD gene (protein tyrosine phosphatase, receptor type, D) is one of 38 known human receptor-type PTPs, a group of proteins that are increasingly thought to be important in human neoplasia and cancer progression." (PMID 25412184, 2014). "A PTPRD mutation annotated as a W775stop germline mutation was found in both the patient's tumor and PBMCs." (PMID 23800680, 2013). "The PTPRD mutation was confirmed by polymerase chain reaction (PCR)-based Sanger sequencing in genomic DNA derived from tumor and PBMCs." (PMID 23800680, 2013). "PTPRD is a candidate tumor suppressor gene that encodes a receptor type protein tyrosine phosphatase." (PMID 18664255, 2008). "The mutation of PTPRD may change the tumor microenvironment (TME), leading to the change of sensitivity to immunotherapy in NSCLC." (PMID 37602864, 2023). "It has been reported that PTPRD has a tumor suppressor function, and mutation of PTPRD may promote tumor growth." (PMID 37602864, 2023). "The PTPRD is a tumor suppressor often inactivated and mutated in tumors." (PMID 37628647, 2023). "Furthermore, we found that two out of those eight gene (CARD11 and PTPRD) mutations were associated with more tumor-infiltrated immune cells in tumor tissues." (PMID 36120536, 2022).
tumor (continued). "While the ANKRD28 gene has an unknown role in GB, the tyrosine phosphatase PTPRD is a tumor suppressor that is frequently inactivated and mutated in GB and other human cancers." (PMID 36132155, 2022). "Furthermore, PTPRD/PTPRT mutations were associated with a higher tumor mutational burden, MSI score, and TCR score (P < 0.0001)." (PMID 36248841, 2022). "In our present study, the mutation frequencies were similar (both about 10%) across tissue and ctDNA cohorts and PTPRD mutations were associated with PFS and ORR in both tissue and ctDNA cohorts; PTPRD mutations in ctDNA were consequently inferred to be consistent with tumor tissue." (PMID 34615542, 2021). "Higher PTPRD expression was associated with fewer anti-tumor, more pro-tumor immune cells." (PMID 34615542, 2021). "Decreased PTPRD expression was associated with diffuse/mixed-type histology, according to the Lauren classification (p < 0.001) and was correlated with tumor invasion depth and regional lymph node (LN) metastasis (p < 0.001)." (PMID 31805999, 2019). "In addition to PTPRT/PTPRD deleterious alterations, univariate Cox regression identified the primary tumor site as a factor associated with PFS." (PMID 30200630, 2018). "Somatic loss of PTPRD has been associated with tumor risk and aggressiveness." (PMID 25138050, 2014). "This is consistent with the hypothesis that the frequently observed heterozygous loss of PTPRD in human cancers contributes to tumor development." (PMID 25138050, 2014). "Although it is possible that patients with specific tumor locations are more likely to harbor PTPRD mutations and could be more likely to be bevacizumab resistant, our cohort only included two patients with splenic flexure tumors, and was therefore not suitable to confirm those results." (PMID 30200630, 2018). "PTPRD (Protein Tyrosine Phosphatase Receptor-Type D) is a broadly inactivated phosphatase/tumor suppressor; multi-cancer screening and real-world datasets identify PTPRD mutation as a recurrent event with clinical impact, including in LUAD." (PMID 41154602, 2025). "Collectively, these data point towards a central role of PTPRD not only as a potential tumour suppressor gene, but also as an orexigenic mediator in EC." (PMID 40871563, 2025). "PTPRD is inactivated in many human cancers and potentially plays a role as a tumor suppressor through STAT3 inhibition." (PMID 39985075, 2025). "Among these genes, CDKN2A, CDKN2B, CUX1, LRP1B and PTPRD were retrieved as tumor suppressors from the TSGene database." (PMID 38831459, 2024). "Alterations in the PTPRD gene affect tumor suppression and cell growth in HNC, suggesting its involvement in disease progression and its potential therapeutic significance." (PMID 39628997, 2024). "PTP receptor type delta (PTPRD) is a tumor suppressor that is negatively correlated with PD-L1, an essential molecule in cancer immune escape." (PMID 36660927, 2023). "The PTPRD mutation was closely related to tumor mutational burden (TMB) and tumor-infiltrating immune cells (TIICs)." (PMID 37602864, 2023). "PTPRD mutation is strongly associated with high TMB levels and immune infiltration and enhanced anti-tumor microenvironment." (PMID 37602864, 2023). "The mRNA level of TP53AIP1 increased methylation of promoter regions in PTPRD gene, which in turn possibly diminished the protein level PTPRD, thereby sensitizing tumor cells to oxaliplatin." (PMID 35853873, 2022). "A splice site mutation c.1544-1G>T of protein tyrosine phosphatase receptor delta (PTPRD) was detected by next-generation sequencing and weak PTPRD expression was confirmed in tumor tissues compared to tumor periphery." (PMID 36034832, 2022). "In brief, PTPRD/PTPRT mutant patients had higher levels of immune cell infiltration, MHC I expression, and other immune signatures, indicating enhanced anti-tumor immunity in PTPRD/PTPRT mutant patients." (PMID 36248841, 2022).